TEX19 (testis expressed 19)
Description:
Required during spermatogenesis and placenta development, participating in the repression of retrotransposable elements and prevent their mobilization. Collaborates with the Piwi-interacting RNA (piRNA) pathway, which mediates the repression of transposable elements during meiosis by forming complexes composed of piRNAs and Piwi proteins. Interacts with Piwi proteins and directly binds piRNAs, a class of 24 to 30 nucleotide RNAs that are generated by a Dicer-independent mechanism and are primarily derived from transposons and other repeated sequence elements. Also during spermatogenesis, promotes, with UBR2, SPO11-dependent recombination foci to accumulate and drive robust homologous chromosome synapsis (By similarity). Interacts with LINE-1 retrotransposon encoded LIRE1, stimulates LIRE1 polyubiquitination, mediated by UBR2, and degradation, inhibiting LINE-1 retrotransposon mobilization.
Synonyms: FLJ35767
Tractability: No criterion of Open Targets' tractability assessment is met for any kind of drug.
Gene: Protein-coding gene on chromosome 17 (82,359,247 to 82,363,775, forward strand). Ensembl gene ENSG00000182459.
Subcellular location: Cytoplasm
Gene Ontology:
Molecular function: protein binding; piRNA binding
Biological process: transposable element silencing; male gonad development; male meiotic nuclear division; placenta development; reciprocal meiotic recombination; spermatogenesis
Cellular component: cytoplasm; nucleus
Genetic constraint (gnomAD): Loss-of-function variants: 0 observed, 0.13 expected, observed/expected ratio (o/e) 0, 90% interval 0 to 1.89. That is too few expected variants to judge how well the gene tolerates losing a copy. Missense variants: 184 observed, 202.25 expected, observed/expected ratio (o/e) 0.91, 90% interval 0.81 to 1.03. Synonymous variants: 77 observed, 78.22 expected, observed/expected ratio (o/e) 0.98, 90% interval 0.82 to 1.19.
Homologues: Orthologues: chimpanzee TEX19 (100% identical), macaque TEX19 (95% identical), rat Tex19.2 (54% identical), mouse Tex19.2 (51% identical), rat Tex19.1 (49% identical), mouse Tex19.1 (45% identical).
Diseases named in the same sentence as TEX19 in open-access papers:
TEX19 is named in the same sentence as 27 diseases in open-access papers, as found by Europe PMC text mining. Sharing a sentence is not in itself a finding about the gene and the disease. The quoted sentences say what the papers report.
bladder cancer (5 papers, 2017 to 2025). "Testis Expressed 19 (TEX19) has been reported to be upregulated in various cancers, including bladder cancer and ovarian cancer, where it promotes tumor progression." (PMID 41233852, 2025). "For example, the expression of TEX19 is higher in high-grade bladder cancer tissues compared to low-grade bladder cancer, suggesting a potential role for TEX19 in the progression of bladder cancer." (PMID 41233852, 2025). "Zhong and co-workers extended their analysis to demonstrate that TEX19 was present in bladder cancer samples." (PMID 28446200, 2017). "Similar results were observed for TEX19 in CC cell lines and bladder cancer." (PMID 35627192, 2022). "For example, TEX19 exhibited increased expression in bladder cancers and might serve as a potential therapeutic target." (PMID 31481019, 2019).
breast carcinoma (4 papers, 2017 to 2025). "In this research, we found that TEX19, the key gene in the signature model, was associated with poor prognosis in breast cancer patients." (PMID 41233852, 2025). "TEX19 was also required to drive cell proliferation in a range of cancer cell types, and its expression was linked to a poor prognosis for breast cancer, kidney cancer, prostate cancer, and glioma cancer." (PMID 31481972, 2019). "In vivo and in vitro experiments using TEX19, the key model gene, knockout cells in nude mice demonstrated a significant reduction in tumor growth, confirming the involvement of TEX19 in breast cancer proliferation." (PMID 41233852, 2025). "Among the 15 model genes, TEX19 showed the highest hazard ratio (HR = 1.313) in univariate Cox regression, highlighting its potential significant impact on the prognosis of breast cancer." (PMID 41233852, 2025). "In vivo and in vitro experiments further validate the critical role of the key model gene TEX19 in driving breast cancer progression." (PMID 41233852, 2025). "In line with our findings, another recent study found that TEX19 promoted the progression of breast cancer by modulating SKP2-mediated ubiquitination of CDK4." (PMID 41233852, 2025). "Single-cell transcriptome data further revealed that TEX19 is predominantly expressed in tumor cells, supporting its biological relevance in breast cancer progression." (PMID 41233852, 2025). "The knockdown of TEX19 inhibited the proliferation of breast cancer cells both in vitro and in vivo." (PMID 41233852, 2025). "Lastly, in vitro and in vivo experiments were conducted to elucidate the role of the key model gene TEX19 in the development of breast cancer." (PMID 41233852, 2025). "To further understand the role of TEX19 played in breast cancer, we generated a TEX19 Knockout MCF-7 cell line." (PMID 41233852, 2025). "TEX19 knockdown inhibited the proliferation and migration of breast cancer cells, increased cell apoptosis, and blocked the cell cycle in the G2 phase." (PMID 38867223, 2024). "Despite these limitations, the analysis of breast cancers and renal cancers clearly indicate a correlative link between high TEX19 expression and poor prognosis, consistent with a functional role for TEX19 as an oncogenic proliferative driver." (PMID 28446200, 2017). "Our analysis of overall survival indicates that for a number of cancers, including breast cancer and renal cancers, that there is a significant correlation between higher TEX19 expression and poor prognosis, supporting a potential functional association." (PMID 28446200, 2017). "Colonies analyses showed that TEX19 is essential for the growth of breast cancer." (PMID 41233852, 2025). "Western blot analysis further confirmed that TEX19 protein was markedly upregulated in breast cancer cell lines (MCF-7, MDA-MB-231, BT-549) compared with the normal mammary epithelial cell line MCF-10A.We selected shTEX19-1, which had a better knockdown effect, for subsequent experiments." (PMID 41233852, 2025).
ovarian carcinoma (3 papers, 2017 to 2025). A malignant neoplasm originating from the surface ovarian epithelium. "TEX19 is also markedly upregulated in ovarian cancer, showing a correlation with advanced TNM stage, and knockdown of TEX19 results in the suppression of proliferation, migration, and invasion of ovarian cancer cells." (PMID 41233852, 2025). "The ovarian carcinoma cell line A2780 showed considerable activation of HERVK gag transcript levels upon a relatively moderate reduction of TEX19." (PMID 28446200, 2017). "Similarly, TEX19, SPAG9, HSP70‐2, and AKAP4 can promote the invasion and metastasis of ovarian cancer, and the downregulation of these genes can significantly inhibit the migration and invasion ability of ovarian cancer cells." (PMID 38896069, 2024).
colon cancer (2 papers, 2017 to 2019). "TEX19 could drive cell proliferation in colon cancers, possibly mediated via an oncogenic transcript regulation mechanism." (PMID 31481019, 2019). "In many of the cell line experiments we conducted we used colon cancer cells, yet interestingly, none of the splits we allocated to colorectal cancer data (263 patients; 124 expressing TEX19 at the threshold set for positive expression) indicated a link to prognosis." (PMID 28446200, 2017).
germ cell tumor (2 papers, 2017 to 2020). A benign or malignant, gonadal or extragonadal neoplasm that originates from germ cells. "Additionally, we note nuclear foci of TEX19 in testis, germ cell tumour line NTERA2 and LMB treated nuclei; the functional relevance, if any, is unknown although it is a noteworthy observation." (PMID 28446200, 2017). "We aimed to assess the prognostic value of previously suggested biomarkers, related to proliferation (MIB-1 and TEX19) and to immune microenvironment (CXCL12, CXCR4, beta-catenin and MECA-79) in a surveillance cohort of stage I testicular germ cell tumor patients." (PMID 32758242, 2020). "Also, for TEX19, a cancer testis antigen present in normal adult testis and involved in proliferation of several cancer types and of germ cells, its expression profile in testicular germ cell tumors has not been demonstrated yet." (PMID 32758242, 2020).
adenoma (1 paper, 2017). A neoplasm arising from the epithelium. "TEX19 was present in all arrays with highest staining observed in the early adenomas (<2 cm), with different levels present in later stage disease tissues." (PMID 28446200, 2017).
breast invasive carcinoma (1 paper, 2017). "For breast invasive carcinoma (BRCA), prostate adenocarcinoma (PRAD) and the pan-kidney cohort (KIPAN) high TEX19 expression is associated with poor prognosis; although the difference is marginal for PRAD." (PMID 28446200, 2017).
breast tumor (1 paper, 2025). "The in vivo and in vitro assays demonstrated that knockdown of TEX19 significantly suppressed breast tumor proliferation." (PMID 41233852, 2025).
cervical squamous cell carcinoma (1 paper, 2017). A squamous cell carcinoma arising from the cervical epithelium. "b Cervical squamous cell carcinoma and endocervical adenocarcinoma (CESC) have reduced overall survival when there is high TEX19 expression." (PMID 28446200, 2017).
colorectal cancer (1 paper, 2017). A primary or metastatic malignant neoplasm that affects the colon or rectum. "The cancerous tissue, however, had regions of strong TEX19 staining demonstrating that TEX19 encodes an antigen within colorectal cancer tissue." (PMID 28446200, 2017). "To determine the stage of tumour progression at which TEX19 becomes apparent, we used IHC to stain colorectal cancer progression arrays." (PMID 28446200, 2017).
glioma (1 paper, 2017). A benign or malignant brain and spinal cord tumor that arises from glial cells (astrocytes, oligodendrocytes, ependymal cells). "Surprisingly, we observed the converse relationship for gliomas where higher TEX19 expression is linked to a better prognosis, suggesting it has favorable activity in neuronal cells." (PMID 28446200, 2017). "c There is a marginal, but significantly better overall survival for lower grade glioma (LGG) patients with high levels of TEX19 expression." (PMID 28446200, 2017). "Intriguingly, higher TEX19 expression is linked to a better prognosis for gliomas (GBMLGG) and brain lower grade glioma (LGG)." (PMID 28446200, 2017).
leukemia (1 paper, 2015). A malignant (clonal) hematologic disorder, involving hematopoietic stem cells and characterized by the presence of primitive or atypical myeloid or lymphoid cells in the bone marrow and the blood. "Interestingly, we also detected Tex19 expression in human neuroblastoma, rhabdomyosarcoma and Jurkat T-cells, i.e., a leukemia cell line." (PMID 26459560, 2015).
lung adenocarcinoma (1 paper, 2024). A carcinoma that arises from the lung and is characterized by the presence of malignant glandular epithelial cells. "Furthermore, the upregulation of TEX19 was found to potentiate glycolysis in lung adenocarcinoma, emphasizing its pro-metabolic function in this context." (PMID 39440050, 2024).
lung carcinoma (1 paper, 2017). "To determine whether nuclear localization of TEX19 is a common feature of cancer cells, we stained a second cell line, H460 (lung carcinoma)." (PMID 28446200, 2017). "Other cells lines previously shown to express TEX19, including an additional colon line (HCT116) as well as a lung cancer line (H460) and an embryonal cancer line (NTERA2), were also employed to assess potential universality of proliferative and/or functional role(s) for TEX19." (PMID 28446200, 2017).
seminoma (1 paper, 2020). A radiosensitive malignant germ cell tumor found in the testis (especially undescended), and extragonadal sites (anterior mediastinum and pineal gland). "In our cohort we did find a weak cytoplasmic staining for TEX19 in a minority of primary tumors (i.e., 14 non-seminomas and one seminoma)." (PMID 32758242, 2020).
cancer (10 papers, 2012 to 2025). A tumor composed of atypical neoplastic, often pleomorphic cells that invade other tissues. "The expression of germline genes has been associated with poor prognosis in various cancers and TEX19 is essential for promoting cell proliferation in diverse cancer cell types, potentially through the regulation of oncogenic transcripts." (PMID 41233852, 2025). "TEX19 protein has been demonstrated to function as a cancer-testis antigen encoded by a gene specific to mammals, situated at 17q25.3 on human chromosome 17." (PMID 41233852, 2025). "The regions of intense TEX19 staining reveal that staining appears to be mostly cytoplasmic, consistent with highly confluent cancer cells and the majority of closely associated cells within colonospheres." (PMID 28446200, 2017). "Transcriptome analysis of TEX19 depleted cells reveals altered transcript levels of a number of cancer-/proliferation-associated genes, suggesting that TEX19 could control oncogenic proliferation via a transcript/transcription regulation pathway." (PMID 28446200, 2017). "TEX19 expression is linked to a poor prognosis for some cancers and collectively these findings indicate that not only can TEX19 expression serve as a novel cancer biomarker, but may also offer a cancer-specific therapeutic target with broad spectrum potential." (PMID 28446200, 2017). "TEX19 was also identified for its role in the progression of bladder and ovarian cancer and was considered as a potential immunotherapeutic target for cancer treatment." (PMID 34036740, 2021). "This supports the advanced role of TEX19 in germ cells, and not only in Sertoli cells, thereby fulfilling the classification of a cancer testis antigen." (PMID 32758242, 2020). "RT-qPCR and RNA sequencing were employed to determine the changes to the transcriptome of cancer cells depleted for TEX19 and Kaplan-Meier plots were generated to explore the relationship between TEX19 expression and prognosis for a range of cancer types." (PMID 28446200, 2017). "Here we find that TEX19 expression is required to maintain the proliferative potential of a range of different cancer cells." (PMID 28446200, 2017). "Whatever the exact role, it is clear that TEX19 expression influences cancer prognosis and should be considered as a highly specific target for the development of novel anti-cancer therapeutic agents." (PMID 28446200, 2017). "For each cohort of cancer patients we divided the population into high and low TEX19 expression groups split by the median value and performed survival analysis." (PMID 28446200, 2017). "TEX19 is required to drive cell proliferation in a range of cancer cell types, possibly mediated via an oncogenic transcript regulation mechanism." (PMID 28446200, 2017). "To expand this observation, we grew colonospheres from SW480 cells, which are enriched for cancer stem-like cells, and assessed TEX19 localization." (PMID 28446200, 2017). "Our finding that human cancer cells have both nuclear/cytoplasmic TEX19, led us to investigate the localization in human cancerous tissues." (PMID 28446200, 2017). "Western blotting, fluorescence activated cell sorting and immunofluorescence were used to study the effect of TEX19 depletion in cancer cells and to localize TEX19 in normal testis and cancer cells/tissues." (PMID 28446200, 2017). "Depletion of TEX19 levels in a range of cancer cell lines in vitro and in vivo restricts cellular proliferation/self-renewal/reduces tumour volume, indicating TEX19 is required for cancer cell proliferative/self-renewal potential." (PMID 28446200, 2017). "This indicates that there are distinct cellular and sub-cellular TEX19 fractions within the testis, consistent with cancer cells." (PMID 28446200, 2017). "We have demonstrated that TEX19 expression is required to maintain proliferation/self-renewal in a range of cancer cell types." (PMID 28446200, 2017).
cancer (continued). "In this study we identify a requirement for TEX19 in human cancer cells to drive proliferation that reveal it to be a potential cancer-specific drug target and prognostic indicator." (PMID 28446200, 2017). "To gain insight into the possible function(s) of TEX19 in cancer cells, we assessed cellular localization." (PMID 28446200, 2017). "Murine Tex19.1 interacts with the E3 ubiquitin ligase Ubr2 which contains a nuclear localization signal, so a role for a UBR2-TEX19 interaction in human cancers would be worthy of further investigation." (PMID 28446200, 2017). "TEX19, known as one of the cancer/testis (CT) genes, might drive cell proliferation in a variety of cancers through the oncogenic transcript regulation mechanism." (PMID 33995635, 2021). "The functional nature of human TEX19 in cancer cells remains unknown, but the TEX19 gene appears to be extensively activated in a range of cancer type." (PMID 31102330, 2019). "As for mouse Tex19.1, TEX19 in cancer cells can operate on a small sub-set of protein coding and/or TE transcripts, although the latter may be indirect." (PMID 28446200, 2017). "This demonstrates that TEX19 is required for proliferation/self-renewal of cancer cells, which could infer such a role in germ and stem cells." (PMID 28446200, 2017). "That TEX19 expression helps drive proliferative potential of cancer cells suggests that it might influence disease progression / outcome in patients." (PMID 28446200, 2017). "The finding that human TEX19 is a CT gene opens the question of whether TEX19 expression is oncogenic or provides a functional advantage to cancer cells." (PMID 28446200, 2017). "To determine whether human TEX19 functions in self-renewal in cancer stem/progenitor cells, we carried out extreme limiting dilution assays (ELDA) to determine self-renewal ability in sphere-derived SW480 cells and NTERA2 cells." (PMID 28446200, 2017). "Given the finding that TEX19 controls cancer cell proliferation we wished to explore whether TEX19 expression influences clinical progression." (PMID 28446200, 2017). "siRNA was used to deplete TEX19 levels in various cancer cell lines." (PMID 28446200, 2017). "Some of the genes, for example, TSN and MYB, are potential regulators of proliferation and so this could indicate that TEX19 is required by cancer cells to drive proliferation by maintaining sufficient levels of oncogenic transcripts." (PMID 28446200, 2017). "This commonality between T-box transcription factors and TEX19 could infer a functional link in the distinct regulation of developmental/proliferative genes in distinct cancer types." (PMID 28446200, 2017). "These analyses might be an underestimation of the influence of TEX19 expression as our analysis was based on splitting cancer patient cohorts based on median TEX19 expression." (PMID 28446200, 2017). "Here we have identified human TEX19 as a driver of cancer cell proliferative potential." (PMID 28446200, 2017). "Given that TEX19 is expressed in many cancer types, this might infer that it is an oncogenic factor, indeed, all cell lines / tumour samples we analysed showed evidence of TEX19 expression." (PMID 28446200, 2017). "Increased data volume and further sub-categorization of tumour types is likely to further resolve which cancer types can be stratified by TEX19 expression profiling, but these initial findings clearly indicate that TEX19 expression is linked to distinct clinical outcomes." (PMID 28446200, 2017). "Loss of murine Tex19.1 can result in spermatogenic cells entering apoptosis, however, analysis of TEX19-depleted human cancer cells indicates that they are likely to be in a quiescent-like state, which appears to be linked to a failure to proceed through S-phase with normal kinetics." (PMID 28446200, 2017).